RNU6-26P (RNA, U6 small nuclear 26, pseudogene)
Synonyms: RNU6-26
Gene: Small nuclear RNA gene on chromosome 3 (98,804,978 to 98,805,084, reverse strand). Ensembl gene ENSG00000206712.
Homologues: Orthologues: chimpanzee U6 (99% identical), pig U6 (89% identical), mouse Gm25811 (80% identical). Paralogues in human: RNU6-12P (96% identical), RNU6-13P (96% identical), RNU6-31P (96% identical), RNU6-32P (96% identical), RNU6-1 (95% identical), RNU6-15P (95% identical), RNU6-17P (95% identical), RNU6-18P (95% identical), RNU6-19P (95% identical), RNU6-2 (95% identical), RNU6-3P (95% identical), RNU6-4P (95% identical), and 1290 more.